LGR5 (leucine rich repeat containing G protein-coupled receptor 5)
Diseases named in the same sentence as LGR5 in open-access papers (continued):
Sharing a sentence is not in itself a finding about the gene and the disease.
colorectal cancer (continued). "Complemented by ex vivo tumor organoid experiments, this study show that Lgr5− colorectal cancer cells have a basal ability to give rise to Lgr5+ cells, and that this process can be boosted by supportive-niche factors like HGF and FGF." (PMID 33671641, 2021). "As reported, RSPO2 suppressed colorectal cancer progression by negatively regulating Wnt/β-catenin signaling through an LGR5-dependent feedback mechanism." (PMID 32018224, 2020). "In colorectal cancer, R-spondin 2 suppresses Wnt signaling in an Lgr5-mediated manner, resulting in a reduction in stem cell properties." (PMID 33126517, 2020). "After TAp63α plasmid transfection, we observed upregulated mRNA and protein levels of Lgr5 in colorectal cancer cells." (PMID 33040081, 2020). "Colorectal cancer stem cells (CSCs) express Lgr5 and display extensive stem cell-like multipotency and self-renewal and are thought to seed metastatic disease." (PMID 32169167, 2020). "Findings from this study suggested therapeutic potential of SFN in the treatment of colorectal cancer through inhibiting colorectal CSCs via targeting TAp63α/Lgr5/β-catenin axis." (PMID 33040081, 2020). "The present study elucidated for the first time that TAp63α promoted CSCs through targeting Lgr5/β-catenin axis and participated in sulforaphane inhibition of the stem cell properties in colorectal cancer." (PMID 33040081, 2020). "This study supports the idea that Lgr5+ cells localized near the colon luminal surface are central to colorectal cancer." (PMID 31947553, 2020). "In patients with colorectal cancer, Lgr5 is an important biomarker of colorectal CSCs, and detecting Lgr5+ CSCs is a crucial indicator to predict tumor recurrence." (PMID 33014829, 2020). "This is the case of antibodies targeting LGR5 which have been reported to have therapeutic activity when conjugated to cytotoxic drugs in mouse models of colorectal cancer." (PMID 32532153, 2020). "LGR5 is a Wnt target gene, which is the marker gene for normal adult intestinal stem cells, and for particularly aggressive colorectal cancer stem cells." (PMID 32403323, 2020). "In normal intestinal cells, Lgr5 expression is an exclusive marker for stemness, while, in colorectal cancer, Lgr5+ cells play an important role in carcinogenesis, but are localized to the luminal surface during early cancer development." (PMID 31947553, 2020). "Generally, numerous reports have indicated that Lgr5 promotes both development and survival of various cancer types through potentiation of Wnt/β-catenin signaling, such as colorectal cancer, and glioblastomas." (PMID 31358061, 2019). "The ability to regenerate Lgr5+ CSCs from other colorectal cancer cells supports epigenetics being a major mechanism regulating CSC plasticity." (PMID 30934773, 2019). "The G protein-coupled receptor LGR5 has also been reported to be a marker for colorectal CSCs during the initial stages of tumorigenesis, and LGR5 expression levels correlated with aggressive clinicopathological features in colorectal cancer." (PMID 31137841, 2019). "Most colorectal cancers contain Lgr5+ cells, which can produce both Lgr5+ and Lgr5− cells, indicative of their self‐renewal and differentiation potential." (PMID 31545551, 2019). "In contrast, a recent study has reported a suppressive role of Lgr5 during the late stages of colorectal cancer progression through attenuation of growth, colony formation, and migration capacities of colon cancer cells." (PMID 31358061, 2019). "LGR5 was found to be overexpressed in colorectal cancer and several studies indicated that LGR5 expression is associated with colorectal carcinogenesis, tumor growth and metastasis." (PMID 30770730, 2019). "It has been reported that LGR5-dependent Wnt/β-catenin-signaling pathway promotes cell proliferation, tumor formation and cancer progression in colorectal cancer, breast cancer and cervical cancer cells." (PMID 30089773, 2018).
colorectal cancer (continued). "Recent studies have better defined the role of LGR5+ cells in the development of human colorectal cancers." (PMID 29652830, 2018). "The decrease of LGR5+ cells in poorly-differentiated colorectal cancers compared to those that are more differentiated suggests that the tumoral de-differentiation process involves the emergence of new de-differentiated cells." (PMID 29652830, 2018). "The inhibition of KDM1A attenuates Wnt/β-catenin signaling and diminishes colorectal cancer progression by downregulating the expression of LGR5." (PMID 29921310, 2018). "In the mouse intestinal polyps, DCLK1+ cells in part co-express other stem-cell-associated markers, such as CD44, LGR5 and CD133; furthermore, DCLK1+ cells have been observed in human colorectal cancers." (PMID 29652830, 2018). "JIB-04 strongly reduced the expression of LGR5 (leucine-rich repeat-containing G-protein-coupled receptor 5) in all three colorectal cancer cell lines." (PMID 29700375, 2018). "Several surface markers were associated with the CSC population in colorectal cancer, such as CD133, CD44v6, Lgr5." (PMID 29902974, 2018). "LGR5 knockdown experiments in colorectal cancer cells showed an increase of the metastatic potential of these cells both in the colon and in the lung." (PMID 29652830, 2018). "A recent study suggests the presences of a special niche of stem-like cells in colorectal cancer with elevated LGR5 expression suggestive of its potential role in metastasis." (PMID 30089773, 2018). "The well characterised deregulation of Wnt/β-catenin signalling that occurs during the adenoma-carcinoma sequence in colorectal cancer (CRC) renders LGR5 an interesting therapeutic target." (PMID 29844449, 2018). "LGR5 serves as a co-receptor for Wnt/β-catenin signalling and marks normal intestinal stem cells; however, its role in colorectal cancer (CRC) remains controversial." (PMID 29149105, 2018). "This methodology was used to visualize the dynamics of LGR5+ cells in human colorectal cancer and to investigate the roles of LGR5+ cells in mouse colorectal cancer." (PMID 29652830, 2018). "In recent years, studies have revealed that Lgr5 is overexpressed in various types of tumors, including colorectal cancer, hepatocellular carcinoma, ovarian cancer, glioma, basal cell carcinoma and gastric carcinoma." (PMID 28404917, 2017). "Studies also indicated that RSPO2 enriches colorectal cancer stem cells by increasing the expression of Lgr5." (PMID 28404917, 2017). "One report showed that there was a connection between CD133 and EGR1 and emphasized the importance of the EGR1/TCF4/CD133/LGR5 network in colorectal cancer." (PMID 29246166, 2017). "Lgr5 is overexpressed in several human tumors, including esophageal adenocarcinoma, gastric cancer, colorectal cancer, hepatocellular carcinoma, ovarian cancer, and brain cancer." (PMID 28404940, 2017). "Other studies have shown that Lgr5 is also overexpressed in tumor spheroid cells in colorectal cancer and breast cancer, similar to our findings." (PMID 28404917, 2017). "Previous studies demonstrated that Lgr5-positive cells were mainly located in the invasive tumor front of colorectal cancer, and significantly correlated with metastasis in regional lymph nodes, distant metastasis, and pTNM stage." (PMID 28404940, 2017). "More recent studies have also defined transcription factors DCLK1 and LGR5 to play a significant role in quiescent and active stem cells in colorectal cancer." (PMID 27668882, 2016). "The methylation status within Lgr5 promoter was detected with a methylation-specific PCR in six colorectal cancer cell lines as well as 169 primary colorectal tumor tissues." (PMID 26599100, 2015). "To evaluate the clinical significance of lgr5 methylation, we analyzed the association between lgr5 promoter methylation status, as determined by MSP, with a variety of clinicopathological features of patients with colorectal cancer." (PMID 26599100, 2015).
colorectal cancer (continued). "To test the potential of DNA methylation in regulating lgr5 expression, we first examined the expression of lgr5 in seven colorectal cancer cell lines and its alteration in response to 5-aza-2’-deoxycytidine (DAC), the classical methylation inhibitor." (PMID 26599100, 2015). "LGR5 has been shown to be highly expressed in a number of cancers, including colorectal cancer, breast cancer, cervical cancer and glioblastoma, where it is associated with positive modulation of Wnt signalling in cancer stem cells." (PMID 26517508, 2015). "MSP analysis on total 169 colorectal cancers revealed that 67 samples (40%) were positive for lgr5 promoter methylation." (PMID 26599100, 2015). "LGR5 expressing cells behave like cancer stem cells (CSCs) in breast and colorectal cancer, glioblastoma, and a mouse-model of papillomavirus-induced squamous cell carcinoma." (PMID 26517508, 2015). "Leucine-rich-repeat-containing G-protein-coupled receptor 5 (lgr5) is a candidate marker for colorectal cancer stem cells (CSC)." (PMID 26599100, 2015). "Next, we investigated promoter methylation of lgr5 gene in normal colon tissues versus colorectal cancer tissues." (PMID 26599100, 2015). "Overall, our study showed that lgr5 methylation isresponsible for lgr5 gene silencing and cancer stem cell differentiation in colorectal cancer." (PMID 26599100, 2015). "Supporting evidence that LGR5 is an important marker of tumor aggressiveness has emerged particularly in the arena of colorectal cancer." (PMID 26416247, 2015). "Lgr5 has recently been identified as a reliable biomarker of cancer stem cells (CSCs) in colorectal cancer (CRC); however, its prognostic value is still controversial." (PMID 26674601, 2015). "Both CD44 and LGR5 are widely recognized as key regulators of the stem cell phenotype, particularly in colorectal cancer." (PMID 25906747, 2015). "Similar to our findings, evaluation of human colorectal tumors by IHC demonstrated that LGR5 over-expression was more frequently found in the metastatic lymph nodes and distant metastases when compared with primary colorectal cancer tissue." (PMID 26416247, 2015). "LGR5 is a target gene of Wnt/β-catenin signaling and is expressed in stem-like cells in colorectal cancers." (PMID 25950950, 2015). "We further investigated the clinical significance of lgr5 methylation in sporadic colorectal cancer." (PMID 26599100, 2015). "This study shows that Lgr5 can be a valuable and reliable prognostic factor of colorectal cancer progression." (PMID 26674601, 2015). "Recent advances in colorectal cancer have led to the characterisation of intestinal stem cell markers, including LGR5, EPHB2, and CD44." (PMID 26367378, 2015). "Lgr5 expression was higher in undifferentiated cells as compared to differentiated cells in colorectal cancer." (PMID 26599100, 2015). "Higher expression levels of these markers are found in colorectal cancer compared to adjacent normal tissue and LGR5 expression positively correlates with the number of lymph node metastases." (PMID 26367378, 2015). "In recent years, many studies have revealed that LGR5 is overexpressed in various types of tumors, including colorectal cancer, ovarian tumor, hepatocellular carcinoma, basal cell carcinoma, and esophageal adenocarcinoma." (PMID 25193857, 2014). "We provide evidence that this gene signature partially overlaps with the Lgr5+ intestinal stem cell signature, and is significantly enriched in normal intestinal stem cells as well as in clinical colorectal cancer samples." (PMID 24651522, 2014). "The contribution of adult intestinal stem cells to colorectal cancer initiation has been studied by transgenic induction of the conditional deletion of APC exclusively in the Lgr5+ intestinal stem cell compartment." (PMID 24920319, 2014). "Although LGR5 allelic variation can affect LGR5 protein expression in colorectal cancers, the somatic LGR5 genotype seems to be relatively stable in primary tumors." (PMID 25192390, 2014).
colorectal cancer (continued). "Leucine-rich repeat-containing G protein-coupled receptor 5 (LGR5) has recently been reported to be a marker of cancer stem cells (CSCs) in colorectal cancer (CRC), and the prognostic value of LGR5 in CRC has been evaluated in several studies." (PMID 25192390, 2014). "Gene expression profiling experiments have also demonstrated that an Lgr5-stem cell gene signature predicts disease relapse in colorectal cancer patients." (PMID 23596566, 2013). "Patients with LGR5+ colorectal cancer and gastric cancer reportedly show shorter survival than patients with LGR5−." (PMID 24133453, 2013). "The role of LGR5 in cancer biology has been well-described, especially in the realm of gastrointestinal cancers, where antibodies to LGR5 can be used to identify colorectal cancer stem cells." (PMID 24252460, 2013). "EPHB2- and LGR5-enriched cells reportedly comprise a stem-like cell population in human colorectal cancers." (PMID 24340024, 2013). "Previous studies demonstrated that Lgr5 is overexpressed in hepatocellular carcinoma, colorectal cancer, ovarian cancer, basal cell carcinoma, and esophageal adenocarcinoma." (PMID 23153436, 2012). "Lgr5 over-expression has been reported in a few cancers, including hepatocellular carcinoma, colorectal cancer, ovarian cancer, basal cell carcinoma, and esophageal adenocarcinoma." (PMID 23153436, 2012). "A very significant difference in Lgr5 expression was found between colorectal carcinoma and normal mucosa (P=0.001)." (PMID 23153436, 2012). "Lgr5 protein was positively expressed in 56.3% (108/192) of the colorectal carcinomas, and 25% (15/60) of distal normal mucosa." (PMID 23153436, 2012). "In this study, we investigated the possible role of Lgr5 expression in clinicopathology and prognosis, as well as the relationship between Lgr5 and Ki-67 in colorectal carcinoma." (PMID 23153436, 2012). "Lgr5 and Ki-67 expression were evaluated by immunohistochemistry in 192 colorectal carcinoma specimens." (PMID 23153436, 2012). "LGR5 levels have profound effects on the anchorage independent proliferation of colorectal cancer cells ‘in vitro’ and ‘in vivo’; however how LGR5 modulates anchorage-independent growth is unclear." (PMID 21829496, 2011). "If overexpression of LGR5 in colorectal cancer cells is mediated by hyper-activated wnt pathway, what role does LGR5 play in wnt responses, and does expression of LGR5 contribute to the maintenance of “cancer stemness”?" (PMID 21829496, 2011). "We have modulated the expression of LGR5 by RNAi (inhibitory RNAs) or overexpression in colorectal cancer cell lines." (PMID 21829496, 2011). "LGR5/GPR49 mRNA is expressed in basal cell carcinoma (tumor of hair follicle), colorectal cancer and in tumors of the colon, ovary and liver." (PMID 21978106, 2011). "Recently and in accordance to our results, Walker and colleagues described that an ablation of LGR5 induces increased invasion and anchorage-independent growth, and enhances tumourigenicity in xenografts experiments of human colorectal cancers." (PMID 21978106, 2011). "This distribution is similar to the distribution of endogenous LGR5 in colorectal cancer cells after wnt stimulation." (PMID 21829496, 2011). "CD44, CD133 and CD166 are adhesion molecules expressed on intestinal stem cells and colorectal cancer stem cells and therefore can be expected to have overlapping expression patterns to LGR5." (PMID 21829496, 2011). "Ablation of LGR5 in colorectal cancer cell lines results in a gene expression pattern consistent with increased canonical wnt signalling." (PMID 21829496, 2011). "As LGR5 appears to be a marker of CCRCs, we have investigated which parameters of cell growth and differentiation are affected by modulation of LGR5 expression in colorectal cancer cell lines." (PMID 21829496, 2011).
colorectal cancer (continued). "LGR5 is a wnt target gene, and the wnt pathway is activated early in the progression of the majority of colorectal cancers through truncations of APC (Adenomatous Polyposis Coli) and, less frequently, mutations of β-catenin." (PMID 21829496, 2011). "We utilized a panel of previously characterized human colorectal carcinoma cell lines to compare LGR5 expression to the expression of another putative intestinal stem cell marker, Musashi-1 (Msi-1)." (PMID 21829496, 2011). "LGR5/GPR49 mRNA expression in colorectal carcinomas correlated significantly with the number of lymph node metastases, lymphatic invasion, and vascular invasion." (PMID 21978106, 2011). "ACVR1 inhibitors may hold therapeutic potential as treatment agents targeting the tumor stroma in colorectal cancer; however, BMPs regulate tissue homeostasis by acting on Lgr5+ stem cells in the intestinal epithelium." (PMID 40745121, 2025). "α-LGR5 detects LGR5 overexpression in >90% of colorectal cancer (CRC), hepatocellular carcinoma (HCC) and pre-B-ALL tumour cells and was used to generate an Antibody-Drug Conjugate (α-LGR5-ADC), Bispecific T-cell Engager (α-LGR5-BiTE) and Chimeric Antigen Receptor (α-LGR5-CAR)." (PMID 39169164, 2024). "Lastly, ongoing research and clinical trials are exploring the efficacy of targeting LGR5 in various stages of colorectal cancer, which could provide more definitive answers in the future." (PMID 39417449, 2024). "Metastatic potential of Lgr5-expressing cells has been reported in colorectal cancer." (PMID 38659853, 2024). "However, the role of LGR5 in colorectal cancer relapse and metastasis has been challenged in the past decade." (PMID 39225547, 2024). "Previous literature indicates that while LGR5 expression may decrease as colorectal cancer advances, it still plays a crucial role in the cancer stem cell population that contributes to tumor growth and metastasis." (PMID 39417449, 2024). "They propose that LGR5 may be an appropriate target for CAR-T cell therapy due to its high expression in colorectal cancer and crucial role in maintaining colorectal cancer stem cells (CSCs)." (PMID 39417449, 2024). "Indeed, LGR5 has been characterized as one of the best stem cell population markers in colorectal cancer." (PMID 39225547, 2024). "Both CD44 and LGR5 are involved in local and liver metastasis in colorectal cancer." (PMID 36831488, 2023). "Additionally, LGR5 is highly expressed in the IV stage of colorectal cancer, being a poor prognosis marker and a potential target of colorectal cancer." (PMID 36835258, 2023). "Aside from the expression of LGR5 in ovarian cancer, its expression in colorectal cancer might also support its suitability as a target antigen in the CAR-T therapy of colorectal cancer." (PMID 38146364, 2023). "Interestingly, the selective activation of intestinal FXR appears to have a protective role, restricting abnormal growth of Lgr5+ cells and potentially curtailing the progression of colorectal cancer (CRC)." (PMID 38069256, 2023). "Colorectal cancer stem cells exhibit enhanced CD44, CD133 and Lgr5 expression; therefore, loss of Fzd7 may initiate tumorigenesis in the colon." (PMID 36691900, 2023). "Intriguingly, colorectal cancer stem cells have high Lgr5 expression." (PMID 37845346, 2023). "The MYC stem gene is activated after Lgr5+ destroys colorectal cancer stem cells in the tumour." (PMID 35563449, 2022). "It has been observed that inhibiting intestinal FXR with DCA may stimulate overgrowth and DNA injury in Lgr5+ cells, which can enhance the generation of colorectal cancer." (PMID 36557741, 2022). "Using the data presented here we propose a modified fitness landscape model of stem cell phenotype in colorectal cancer, where Lgr5+ve CBCs and Lgr5−ve RSCs represent distinct but interlinked and equilibrated stem cell population peaks situated along a phenotypic axis." (PMID 35931031, 2022).